HIC1 (HIC ZBTB transcriptional repressor 1)
Diseases named in the same sentence as HIC1 in open-access papers (continued):
Sharing a sentence is not in itself a finding about the gene and the disease.
esophageal varices (1 paper, 2015). Abnormally dilated veins of the esophagus. "Meanwhile, we examined mRNA expression of HIC1 in esophageal epithelium atypical hyperplasia (n = 15), esophagitis (n = 10), and esophageal varices specimens (n = 5)." (PMID 26510908, 2015).
germinoma (1 paper, 2020). A malignant germ cell tumor arising in the central nervous system. "While this particular sample showed higher expression of GATA6, FOXA2, or HNF4A and hypermethylation of RASSF1, RUNX3, HIC1, or APC, its methylation pattern was partially common to that of germinomas or ECs." (PMID 32999426, 2020).
HIV-1 infection (1 paper, 2016). The type species of lentivirus and the etiologic agent of acquired immunodeficiency syndrome (AIDS). "Among the cellular target genes regulated by HIC1, CTIP2 and HMGA1 are several, which have been reported to be involved in HIV-1 infection." (PMID 27725726, 2016).
hyperplastic polyp (1 paper, 2012). A polyp found mainly in the stomach and colon. "Fecal screening for CRC with hypermethylated HIC1 gene detection compared with FOBT has shown promising results for this epigenetic marker in 26 patients with CRC, 13 with adenoma (≥1 cm), 9 with hyperplastic polyps, 9 with chronic inflammatory bowel disease, and 32 normal-controls." (PMID 22969796, 2012).
invasive carcinoma (1 paper, 2025). A carcinoma that is not confined to the epithelium, and has spread to the surrounding stroma. "DNA methylation patterns involving genes like CCNA1, C13ORF18, DAPK, HIC-1, HIN-1, MGMT, RAR-beta, and RASSF1A were also modeled as influential epigenetic factors affecting different transition states from normal tissue to invasive carcinoma." (PMID 40649795, 2025).
Male germ cell tumor (1 paper, 2023). "have reported that the promoter hypermethylation of HIC1 was involved in the resistance of Male germ cell tumor (GCT) to cisplatin." (PMID 37388742, 2023).
meningioma (1 paper, 2022). A generally slow growing tumor attached to the dura mater. "The different statistical analysis shows interesting interrelations between apoptotic genes and autophagy, and a surprising involvement of GSTP1, BCL2 DAPK1, and HIC1 that deserves further consideration in meningioma." (PMID 36011000, 2022).
metastatic tumor (1 paper, 2012). "In our data, the most remarkable change in metastatic tumor was occurred at increases (≧1.30) of D1S1635 (1p36.22), D1S214 (1p36.31), EXT1 (8q24.11-q24), AFM137XA11 (9p11.2), CCND2 (12p13), 8 M16/SP6 (12ptel), IGH (D14S308), HIC1 (17p13.3), 282 M15/SP16 (17ptel), and LAMA3 (18q11.2)." (PMID 23199169, 2012).
omphalocele (1 paper, 2025). Omphalocele is an embryopathy classified in the group of abdominal celosomias and is characterized by a large hernia of the abdominal wall, centered on the umbilical cord, in which the protruding viscera are protected by a sac. "The findings of this study indicate that PAFAH1B1, YWHAE and CRK are associated with major phenotypes of 17p13.3, and RTN4RL1 may be involved in white matter changes and HIC1 might contribute to the occurrence of omphalocele." (PMID 40390087, 2025). "While PAFAH1B1, YWHAE and CRK are associated with major phenotypes of 17p13.3, RTN4RL1 may be involved in white matter changes and HIC1 might contribute to the occurrence of omphalocele." (PMID 40390087, 2025).
orofacial clefting (1 paper, 2010). "In conclusion, with the possible exception of FLNB, HIC1 and ZNF189, our data suggest that maternal genes do not contribute significantly to orofacial clefting in the Norwegian and Danish samples." (PMID 20634891, 2010).
pancreatic ductal adenocarcinoma (1 paper, 2018). An infiltrating adenocarcinoma that arises from the epithelial cells of the pancreas. "For example, HIC-1 mRNA and protein levels were reported to be low or absent in pancreatic ductal adenocarcinoma (PDAC) tissues, and its expression gradually decreased during the progression of PDAC; negative HIC-1 expression predicted advanced pathological stage and poor patient survival." (PMID 30202238, 2018).
prostate tumors (1 paper, 2020). "For the analyses of normal prostate and prostate tumors, we used an antibody (Abcam ab33029) recommended for IHC studies that we also validated for the detection of endogenous HIC1 proteins by immunoblotting." (PMID 33227080, 2020). "Thus, HIC1 expression is detectable in prostate tumor tissues and a trend is observed with the amount of stroma present in our cohort of samples." (PMID 33227080, 2020). "Our studies provide new insights into the role of HIC1 in normal prostatic epithelial-stromal interactions through direct repression of CXCL12 and new mechanistic clues on how its loss of function through promoter hypermethylation during aging could contribute to prostatic tumors." (PMID 33227080, 2020).
thyroid tumor (1 paper, 2016). A benign or malignant neoplasm affecting the thyroid gland. "Compared to normal thyroid tissue, thyroid tumors had lower expression of HIC1 and higher SIRT1 expression." (PMID 27793057, 2016).
tumor (105 papers, 1997 to 2025). "The correlations between HIC1 and tumor mutation burden (TMB), microsatellite instability (MSI), and the immunotherapy efficacy of PD-1/PD-L1 inhibitors were analyzed by Spearman correlation analysis." (PMID 37388742, 2023). "Our results showed that HIC1 expression was mainly associated with T cells, B cells, macrophages, and mast cells in the tumor immune microenvironment in multiple cancers." (PMID 37388742, 2023). "SIRT1, as an important transcriptional target of HIC1, is transcriptionally upregulated in tumor cells due to the loss of HIC1." (PMID 34642302, 2021). "Kaiso causes transcriptional repression of several well-known tumor suppressor genes like Retinoblastoma (Rb), Hypermethylated In Cancer 1 (HIC1) and Cyclin-Dependent Kinase Inhibitor 1A (CDKN1A)." (PMID 31245293, 2019). "Downregulation of the novel tumor suppressor gene HIC1 (hypermethylated in cancer 1) occurs frequently in various tumors where it causes tumor progression and metastasis." (PMID 26510908, 2015). "In contrast, HIC1 is a candidate tumor suppressor that is often found mutated or hypermethylated in human cancer." (PMID 22662240, 2012). "In this study, we determined that the expression levels of HIC1, which are associated with tumor migration, invasion, and metastasis, were associated with TNBC subtypes: basal-like (MDA-MB-468 and HCC38), mesenchymal-like (MDA-MB-231), and luminal androgen receptor (MDA-MB-453)." (PMID 39339179, 2024). "HIC1 played as a tumor suppressor by hypermethylation mediated function loss." (PMID 36131791, 2022). "Loss of HIC1 expression in the early stages of tumor formation may contribute to malignant transformation through the acquisition of chromosomal instability." (PMID 34299935, 2021). "Consistent with our data showing that HIC1 overexpression suppressed HCT116 cell growth and clonogenic activity, depletion of Hic1 in mice promoted both polyp formation in cooperation with loss of the tumor suppressor Apc and chemical carcinogenesis in the colon." (PMID 32457453, 2020). "For instance, methylation of HIC ZBTB Transcriptional Repressor 1 (HIC1) and Ras Association Domain Family Member 1 (RassF1A) tumor suppressor genes was sufficient to transform bone marrow MSCs into malignant cells endowed with tumor‐initiating capabilities." (PMID 32922961, 2020). "Together, these data indicated that HIC1 might have a clinical significance as a marker associated with negative regulation of tumor progression in ESCC." (PMID 26510908, 2015). "HIC-1 promoter hypermethylation is associated with tumor aggressiveness and poor survival." (PMID 25435951, 2015). "As expected, significant differences were observed in the methylation pattern between normal and cancer cells, and genes encoding three tumour suppressor proteins (HIC1, RASSF1A, and p73) displayed an increased percentage of promoter hypermethylation in cancer cells compared with non-tumour cells." (PMID 23251702, 2012). "The PD‐L1 antibody group partially impeded tumor progression, and the synergistic effect of HIC1 overexpression combined with PD‐L1 antibody further augmented the anti‐tumor response." (PMID 40279559, 2025). "The results demonstrate that castration treatment was ineffective in the low‐expression HIC1 group compared to the sh‐NC group, whereas the average tumor volume decreased in the EPI‐7170 and NT157 treatment groups." (PMID 41050263, 2025).
tumor (continued). "Subsequently, we implanted MFC cells with HIC1 overexpression into C57BL/6J mice (immunocompetent) and found that HIC1 overexpression exhibited a stronger inhibition impact on tumor volumes and weights than controls, as well as BALB/C nude mice." (PMID 40279559, 2025). "Herein, we not only highlighted the pivotal role of HIC1 in recruiting the CD8+ T cells to infiltrate the tumor but also its synergy with PD‐L1 antibodies in enhancing antitumor immune responses." (PMID 40279559, 2025). "The co‐treatment of HIC1 with the GSDMD inhibitor DMF led to an augmentation in both tumor volume and weight." (PMID 40279559, 2025). "When the tumor growth in the low‐expression HIC1 group reached 300 mm3, the mice were castrated and randomly assigned to either the EPI‐7170 or NT157 group." (PMID 41050263, 2025). "In vivo experiments displayed that overexpression of HIC1 impeded tumor growth in BALB/C nude and C57BL/6J mice models." (PMID 40279559, 2025). "HIC1 is a tumour suppressor gene located at chromosome 17p13.3, and has been reported to induce endothelial to mesenchymal transition with depletion." (PMID 38686489, 2024). "Overall, HIC1 expression was mainly correlated with T cells, B cells, macrophages, and mast cells within the tumor immune microenvironment in multiple cancer types." (PMID 37388742, 2023). "It has been reported that deletion of HIC1 can contribute to premalignant transformation in the early stage of tumor formation." (PMID 37388742, 2023). "Although growing evidence has supported the critical roles of HIC1 in cancer initiation and development, its roles in tumor immune microenvironment and immunotherapy are still unclear, and no comprehensive pan-cancer analysis of HIC1 has been conducted." (PMID 37388742, 2023). "To further uncover the potential immunomodulatory functions of HIC1 in tumor immunity, we employed the ESTIMATE algorithm, CIBERSORT algorithm, and TISIDB databases to investigate the correlations of HIC1 with the tumor immune microenvironment in pan-cancer." (PMID 37388742, 2023). "HIC1 is frequently hypermethylated which lead to the inactivation of HIC1 in the development of tumor." (PMID 37388742, 2023). "HIC1 expression in pan-cancer, and differential HIC1 expression between tumor and normal samples were investigated." (PMID 37388742, 2023). "For example, in the first mode, a driver-upregulating mutation in the regulatory region of CCND1 (Cyclin D1) is predicted to break binding of HIC1, a transcriptional repressor TF and a candidate tumour suppressor gene." (PMID 36625266, 2023). "By comparing HIC1 expression between TCGA tumor samples and GTEx normal samples, upregulation of HIC1 was also detected in GBM, LAML, PAAD, and STAD, and downregulation of HIC1 was also found in ACC, ESCA, LGG, LIHC, OV, PRAD, SKCM, and UCS." (PMID 37388742, 2023). "Thus, specific methylation of HIC1 could predispose cells to tumor development." (PMID 35251985, 2022). "Analysis of the TCGA+ GTEx and GSE40272 datasets indicated that HIC1 expression in tumor tissue was lower than that in adjacent normal prostate tissue for both." (PMID 35853880, 2022). "Previous reports have suggested that promoter hypermethylation is the main reason for the decrease of HIC1 in tumor tissues." (PMID 35501800, 2022). "Taken together, these findings suggest that knockout of Hic1 accelerated tumor onset and induced more M2 macrophage infiltration." (PMID 35853880, 2022). "FBXW11 overexpression accelerated the degradation of the HIC1 protein in tumor cells, whereas the knockdown of FBXW11 decelerated this process compared to cells with normal FBXW11 expression." (PMID 34642302, 2021).
tumor (continued). "Six overall survival associated genes (ENPP2, ULK1, CP, LURAP1L, HIC1, AKR1C1) were selected to build survival model, of which hub gene AKR1C1 was with high expression and low ferroptosis level in NSCLC tumor." (PMID 34702254, 2021). "A single type of CDKN2A alteration (c.343G>T: p.Val115Leu) was detected in an AA sample, and a single type of HIC1 alteration (c.1571A>G: p.Lys524Arg) was confirmed in an AA tumor." (PMID 33778063, 2021). "Using this antibody, we showed that HIC1 is undetectable in epithelial cells but rather is detected in the normal and tumor stroma." (PMID 33227080, 2020). "We report a significantly elevated HIC1 promoter methylation in tumor samples compared to normal (OR = 7.02, 95 % CI 3.12-15.78, P < 0.001) and benign controls (OR = 2.69, 95 % CI 1.13-6.42, P = 0.025)." (PMID 32398971, 2020). "Our findings revealed a significantly elevated HIC1 promoter methylation in tumor compared to the healthy and benign controls." (PMID 32398971, 2020). "Here, we demonstrated by immunohistochemistry that detectable HIC1 expression is restricted to the stroma of both normal and tumor prostate tissues." (PMID 33227080, 2020). "Among the potential target genes of miRNA-328-5p, the DAB2IP, NFIC, IL-27, and HIC1 genes were tumor suppressors." (PMID 31776329, 2019). "HIC-1 is a tumor-suppressor gene that is frequently epigenetically silenced or deleted in many human cancers." (PMID 30202238, 2018). "These correlated sequential events indicated that concurrent HIC1 and RassF1A methylation potentially plays a role in tumor expansion." (PMID 30249017, 2018). "Meanwhile, restoring HIC1 expression in several PCa cell lines markedly inhibits cell proliferation, migration and invasion in vitro, as well as reduces tumor growth, tissue metastasis and bone destruction in vivo." (PMID 28973968, 2017). "HIC1 is a tumor suppressor gene located at 17p13.3, a chromosomal region that is frequently hyper-methylated or deleted in human tumors." (PMID 28973968, 2017). "HIC1 is a tumor suppressor and a transcriptional repressor, which inhibits E2F1 transcription through the recruitment of SWI/SNF complex by a direct interaction with ARID1A." (PMID 27323812, 2016). "Our results decipher the mechanism through which HIC1 deficiency induce ESCC cells to undergo EMT and promote tumor progression and metastasis through activation of EphA2 signaling pathway." (PMID 26510908, 2015). "Results showed that HIC1 expression was significantly reduced in the majority of ESCC tissues compared with adjacent non-tumor tissues, which was similar to other tumors." (PMID 26510908, 2015). "Using these cell models, the effects of upregulating the HIC-1 gene were explored in multiple biological features, including tumor growth, migration, invasion and the cell cycle." (PMID 25435951, 2015). "According to Knudson’s theory of inactivation of tumor suppressor genes, if Hic1, Inpp5k and Myo1c are to behave as classical tumor suppressor genes, it is expected that both alleles of the genes be inactivated in the tumor material." (PMID 26170120, 2015). "There are 19 genes located in this segment, including several putative tumor suppressor genes, notably Hic1 (hypermethyalted in cancer 1), Ovca1 (ovarian cancer-associated gene 1), and Ovca2 (ovarian cancer-associated gene 2)." (PMID 26170120, 2015).